KRAS (KRas proto-oncogene, GTPase)
Diseases named in the same sentence as KRAS in open-access papers (continued):
Sharing a sentence is not in itself a finding about the gene and the disease.
pancreatic cancer (continued). "Knocking down PIP5K1A expression specifically reduced the viability of KRAS transformed cells versus NRAS or HRAS mutated cancer cells and had an additive effect with MEK inhibitors in KRAS mutant pancreatic cancer cell models." (PMID 33562401, 2021). "Similar to pancreatic cancer cells that express c-MYC or mutant KRAS in a ligand-controlled manner, the survival of KRASG12D-expressing mammary tumor cells that are being maintained in culture did not rely on the oncogenic driver." (PMID 34145248, 2021). "KRAS has a large odds ratio for pancreas cancer, with the specific hotspots KRAS G12D and KRAS G12R providing additional discriminative information captured by the “residual” effects at the variant level." (PMID 34031376, 2021). "These topics include the impact of obesity on KRAS activity, the role of visceral adipose tissue, intrapancreatic fat, adipose tissue inflammation, and adipokines on pancreatic cancer development." (PMID 34680216, 2021). "Strikingly, signaling downstream of mutant KRAS in pancreatic cancers leads to mitochondrial fragmentation and increased activation of Drp1, processes that are required for KRAS-driven tumor growth in vivo." (PMID 33498743, 2021). "AZD4547 profoundly and synergistically enhanced the anti‐proliferative effect of BI2536 in KRAS‐mutant lung and pancreatic cancer cells, although AZD4547 (5 μM) and BI2536 (5 nM) alone at the tested dosage only mildly to moderately affected cell growth." (PMID 34369083, 2021). "Our results suggest that the KRAS/Lin28B axis drives the let‐7i/TET3 pathway to maintain the stemness of pancreatic cancer cells." (PMID 33107691, 2021). "The use of KRAS as a therapeutic target for pancreatic cancer has been studied extensively in recent years." (PMID 38107772, 2021). "For example, one important signaling axis in pancreatic cancer metastasis is the KRAS/NF-kb/YY1/miR-489." (PMID 33466892, 2021). "Using two different mouse models for the prevalent CUX1 isoforms p200 and p110, we identified p110 CUX1 as the major isoform promoting pancreatic cancer formation in the context of mutant KRAS." (PMID 34070180, 2021). "Given the frequent occurrence of activating mutations in KRAS in human pancreatic cancer, the first efforts of modeling PDAC in mice concentrated on the targeted expression of oncogenic KRAS to the exocrine pancreas." (PMID 34491463, 2021). "In a transgenic mouse model of pancreatic cancer, cell survival following KRAS ablation depends on mitochondrial function, especially oxidative phosphorylation." (PMID 33676427, 2021). "They reported that abnormalities in genes of the RAS pathway other than KRAS were observed in approximately 60% of the KRAS wild-type pancreatic cancers." (PMID 33562094, 2021).
pancreatic cancer (continued). "In this study, they aimed to understand KRAS dependency of pancreatic tumor cells, in terms of tumor progression and maintenance based on the cells’ tumorigenic capacity and immune suppression abilities." (PMID 34781949, 2021). "It has been reported that oncogenic KRAS mutations, and subsequent activation of the downstream effectors, such as Erk, Akt, and MEK, can result in the modulation of pancreatic cancer." (PMID 33643376, 2021). "This study elucidates the distinct mechanism of Lin28B nuclear translocation, and illustrates a new pathway of KRAS‐driven pancreatic cancer." (PMID 33107691, 2021). "According to the dbSNP database from the National Institutes of Health, rs12193529 has an effect on KRAS protein variants G12D and GLY12ASP and is associated with the growth and metastasis of pancreatic tumor." (PMID 34901786, 2021). "This study used the mCherry-EGFP-LC3B autophagy reporter assay and the bafilomycin clamp assay to demonstrate increased autophagic flux under KRAS suppression in pancreatic cancer cells." (PMID 34830283, 2021). "SGs are among the primary responses to stimulation in the survival of mutant KRAS pancreatic cancer cells compared to KRAS-WT cancer cells." (PMID 34604242, 2021). "Pancreatic tumors from HN and BT shared a similar KRAS subtype distribution pattern, predominately KRAS p.G12D, followed by KRAS p.G12V and KRAS p.G12R (upper)." (PMID 33350171, 2021). "Approximately 90% of the pancreatic cancer genomes sequenced using targeted sequencing, whole-exome sequencing, or whole-genome sequencing exhibited carcinogenic KRAS." (PMID 34134622, 2021). "Another genome-wide genetic rescue screen revealed that autocrine IGF1/AKT signaling was a common survival mechanism following KRAS depletion in a doxycycline-inducible Kras G12D pancreatic cancer mouse model." (PMID 34680229, 2021). "Mutant KRAS lung and pancreatic cancer patients with high FOSL1 expression had the worst survival outcome." (PMID 34503105, 2021). "Over 90% of pancreatic cancers contain genetic changes that increase the activity of a protein called KRAS." (PMID 34590580, 2021). "c-MYC acts as a cooperative downstream oncogenic factor to KRAS and has been shown to be overexpressed in both primary and metastatic pancreatic tumors." (PMID 34947972, 2021). "This study aimed to explore the regulatory mechanism of hsa-miR-143-3p and lncRNA RP11-363N22.3–functioning upstream of KRAS–in exosomes derived from human mesenchymal stem cells (hMSCs) in pancreatic cancer." (PMID 33643376, 2021). "In SCCHN, miR-193b acts as an oncogene through its action on NF1, and in pancreatic cancer, it acts as a tumor suppressor by directly targeting KRAS through AKT, ERK, and MAPK pathways." (PMID 34199293, 2021). "Tissue markers that are differentially expressed in pancreatic cancer (CEA, mucin-1 (MUC-1)), mesothelin, mutated KRAS G12, CA19-9, carcinoembryonic antigen-related cell adhesion molecule 6 (CEACAM6) have been recently studied as potentials vaccine targets." (PMID 33546207, 2021). "Oncogenic KRAS up-regulates antioxidant defense systems via various mechanisms, counteracting the excessive ROS accumulation during pancreatic cancer progression." (PMID 33546421, 2021). "In this work, we developed a biocompatible HAp-PEI nanoparticle as an efficient carrier to deliver KRAS-siRNA for anti-pancreatic cancer therapy." (PMID 34575504, 2021). "For example, KRAS was found to promote glutamine metabolism and control pancreatic cancer chemoresistance by upregulating the expression of the antioxidant NRF2." (PMID 34947990, 2021). "An understanding of the regulatory mechanisms of miRNA and lncRNA that function upstream of KRAS in pancreatic cancer will be extremely valuable." (PMID 33643376, 2021).
pancreatic cancer (continued). "MIA-PACA2 cells—KRAS-transformed pancreatic cancer cells—express Phafin2, and GFP-tagged Phafin2 labeled large vesicles and showed a biphasic localization pattern in these cells." (PMID 34772942, 2021). "In a pancreatic cancer mouse model, mutant KRAS induced the expression of Sonic hedgehog, which in turn activated the transcription factor GLI1." (PMID 33777798, 2021). "A recent study in support of similar synergy proposed the combination of KRAS-G12C plus mTORC1/2 inhibitors which reliably suppressed pERK and pAKT and induced cell death in pancreatic cancer models." (PMID 34200676, 2021). "The discovery of recurrent fusions involving NRG1 in KRAS wild-type pancreatic tumors, as well as case reports of fusions involving BRAF, PRKACA, NTRK1/3, and RET, prompted us to systematically screen for fusion genes in this cancer entity." (PMID 33441414, 2021). "In KRAS G12D mouse model of pancreatic cancer surviving cells responsible for tumor relapse rely on oxidative phosphorylation, making the combined inhibition of the KRAS pathway and mitochondrial respiration a possible therapeutic strategy." (PMID 33777798, 2021). "Our data and reports from literature support these findings indicating that KRAS-mutant pancreatic cancer cells harbor significant cathepsin L activity." (PMID 34070180, 2021). "As evident, there is an extensive contribution of KRAS in the development and progress of pancreatic cancer, in addition to other genetic or epigenetic factors." (PMID 34781949, 2021). "According to growing evidence linking KRAS mutations to increased PDAC growth, the National Cancer Institute identified the targeting of KRAS as one of four major priorities for pancreatic cancer research." (PMID 34298594, 2021). "The anticancer efficacy of them have negligible effects on patients with pancreatic cancer, especially in KRAS mutant pancreatic ductal adenocarcinoma." (PMID 34376189, 2021). "Suppression of ICMT inhibits cancer stem cell self-renewal and chemoresistance of mutant KRAS pancreatic cancer cells with TAZ protein degradation." (PMID 34395269, 2021). "There is also a phase I/II clinical trial that examines KRAS mutant pancreatic cancer and combines three treatments: cobimetinib, HCQ, and atezolizumab, a PD-L1 antibody." (PMID 34830283, 2021). "Inhibition of PDEδ by deltarasin in human KRAS-mutant pancreatic cancer cell lines blocks the localization of KRAS to the plasma membrane and impairs their proliferative capacity." (PMID 34947990, 2021). "RAS genes (KRAS, NRAS and HRAS) represent the most frequently mutated oncogenes in human cancer including pancreatic cancer." (PMID 33632214, 2021). "KRAS-driven pancreatic cancer cells rely mainly on glutamine for their ability to survive in low glucose and amino acid environments, and are unable to survive glutamine deprivation even in the presence of other nutrients." (PMID 34064761, 2021). "The miRNA-96 served as a tumor suppressor gene in pancreatic cancer, decreased cell invasion, migration and growth through inhibiting KRAS." (PMID 34338136, 2021). "By inhibiting some of the specific signal pathways, such as the Src signal pathway or the KRas signal pathway, these medicines also appear to work efficiently on pancreatic carcinoma." (PMID 33661942, 2021). "We have previously shown that Gal-3 gives rise to KRAS addiction by directly binding to the cell surface receptor integrin αvβ3 in non-small cell lung cancer and pancreatic carcinoma cells." (PMID 34112916, 2021).
pancreatic cancer (continued). "PI3K has been shown to compensate for KRAS suppression in pancreatic cancer cells and regulate epigenetic modifiers including DNMTs42." (PMID 32576853, 2020). "Subsequent studies validated that restoration of miR-143 34 or miR-145 35 retard the transformation of pancreatic cancer at least partly through downregulation of KRAS and RREB1." (PMID 32210733, 2020). "Oncogenic KRAS induces Nrf2 transcription and promotes ROS detoxification that supports pancreatic tumor maintenance." (PMID 32978257, 2020). "Simultaneous mutation of KRAS and BRAF is very rare in pancreatic cancer, similar to mutations of the lipid signaling pathways." (PMID 32725342, 2020). "In contrast, a peptidomimetic inhibitor of ADAM8 reduced tumour growth of pancreatic tumour cells in a xenograft model but was also able to impair tumour growth in a KRAS-driven pancreas cancer model and significantly prolonged overall survival." (PMID 32698506, 2020). "In pancreatic cancer, the Kirsten rat sarcoma viral oncogene homolog (KRAS) gene reprograms glutamine metabolism by upregulating aspartate transaminase (GOT1) and repressing GLUD1 to increase the NADPH/NADP(+) ratio for stable redox capacity." (PMID 33511116, 2020). "Predictably, all patient-derived pancreatic cancer cell lines (PDCL5 and PDCL15) used in our recent study contain oncogenic KRAS mutations." (PMID 33233470, 2020). "Recently, it has been investigated the role of a metabolic regulator that prevents obesity, fibroblast growth factor 21 (FGF21), in KRAS oncogenic context of pancreatic cancer." (PMID 32411709, 2020). "In line, a phase I trial is recruiting patients with KRAS+ metastatic pancreatic cancer to study the best dose of hydroxychloroquine when given together with the MEK1/2 inhibitor binimetinib (NCT04132505)." (PMID 32560574, 2020). "It has been shown that plasma BCAAs levels are elevated in early-stage pancreatic cancers driven by mutant KRAS." (PMID 33117704, 2020). "A clinically advanced example of this approach is represented by the delivery of engineered exosomes loaded with mutant KRAS-targeting siRNAs to inhibit pancreatic cancer." (PMID 32117755, 2020). "Comparable to observations in pancreatic cancer, genetic ablation of autophagy in KRAS-driven CRC tumors can either promote or inhibit tumor growth driven by activation of different signaling pathways." (PMID 32878084, 2020). "In vitro and in vivo assessment of ADC activity was performed in KRAS mutant pancreatic cancer (PaCa) models with known resistance to CTX therapy." (PMID 32913288, 2020).
pancreatic cancer (continued). "We identified MiR181ab1 as a miRNA cluster upregulated by oncogenic KRAS and used multiple genetically engineered mouse models (GEMMs) to demonstrate a role for this cluster in both initiation and maintenance of lung and pancreatic cancer." (PMID 31874105, 2020). "In 9 of 10 oncogenic KRAS pancreatic tumor samples, the "water-burst" method resulted in a positive mutation call." (PMID 32704002, 2020). "A similar mechanism for mutant KRAS pathway activation was found for other lncRNAs in pancreatic cancer—NUTF2P3-001 and UCA1." (PMID 32545208, 2020). "Both nelfinavir and the PI3K inhibitor LY294002, decreased phosphorylation of Akt in pancreatic cancer cells expressing either wild type or mutant KRAS, and sensitized them to radiation." (PMID 33228205, 2020). "Proteomic analysis reveals the selective enrichment of known exosome markers and also signaling proteins involved in pancreatic cancer progression (KRAS, CD44, and EGFR) in oncogenic exosomes compared to exosomes from non-malignant cells." (PMID 32974169, 2020). "Several statins, comprising natural ones (lovastatin and simvastatin), efficiently inhibited KRas protein trafficking from the cytoplasm to the cell membrane of pancreatic cancer cells due to depletion of the mevalonate pathway intermediates." (PMID 33182807, 2020). "Mutations in the KRAS gene, which is an important member of the RAS oncogenic family, have been observed in at least 90% of pancreatic cancer patients." (PMID 32532955, 2020). "Activation of GLI transcription factors is required for formation of oncogenic KRAS-dependent pancreatic cancer in mice." (PMID 33333727, 2020). "Here we analyzed the basal CpG methylation of 11 KRAS-mutant and dependent pancreatic cancer cell lines and observed strikingly similar methylation patterns." (PMID 32576853, 2020). "RREB1 is also involved in the KRAS-induced transformation of pancreatic cancer via repressing the tumor suppressor miR-143/145." (PMID 32210733, 2020). "This evidence highlight the relevance of KRAS-induced autophagy in the malignant transformation of pancreatic tumor cells." (PMID 32655498, 2020). "In an effort to verify the pancreatic cancer identity of the three CTC-derived cell lines, we evaluated the KRAS mutation status of our cell lines and detected a heterozygous G12/G13 mutation in all three CTC cell lines." (PMID 32326109, 2020). "Our observation that 1E5 has a more potent effect in KRAS mutant cells than KRAS wild-type cells further supports the current efforts in targeting mutant KRAS-induced pathways in pancreatic cancer." (PMID 33348693, 2020).